ZNF596 (zinc finger protein 596)
Description:
May be involved in transcriptional regulation.
Tractability: No criterion of Open Targets' tractability assessment is met for any kind of drug.
Gene: Protein-coding gene on chromosome 8 (232,137 to 264,703, forward strand). Ensembl gene ENSG00000172748.
Subcellular location: Nucleus
Subcellular location (Human Protein Atlas): Mitochondria; Nucleoli
Pathways (Reactome):
Gene expression (Transcription): Generic Transcription Pathway
Gene Ontology:
Molecular function: protein binding; DNA-binding transcription factor activity, RNA polymerase II-specific; RNA polymerase II transcription regulatory region sequence-specific DNA binding
Biological process: regulation of transcription by RNA polymerase II; regulation of DNA-templated transcription
Cellular component: nucleus
Genetic constraint (gnomAD): Loss-of-function variants: 43 observed, 47.85 expected, observed/expected ratio (o/e) 0.9, 90% interval 0.7 to 1.16. The synonymous counts are far from expectation, so gnomAD's model fits this gene poorly and the ratio says little. Missense variants: 844 observed, 624.78 expected, observed/expected ratio (o/e) 1.35, 90% interval 1.28 to 1.43. Synonymous variants: 270 observed, 212.15 expected, observed/expected ratio (o/e) 1.27, 90% interval 1.15 to 1.41.
Homologues: Orthologues: chimpanzee ZNF596 (99% identical), macaque ZNF596 (93% identical), pig ZNF596 (74% identical), dog ZNF596 (69% identical), Drosophila melanogaster CG3281 (25% identical), Drosophila melanogaster CG2712 (23% identical), Drosophila melanogaster Phs (23% identical). Paralogues in human: ZNF555 (44% identical), ZNF20 (42% identical), ZNF69 (42% identical), ZNF805 (41% identical), ZNF266 (41% identical), ZFP90 (41% identical), ZNF264 (40% identical), ZNF599 (40% identical), ZNF560 (40% identical), ZNF778 (40% identical), ZNF440 (39% identical), ZNF77 (39% identical), and 50 more.
Diseases named in the same sentence as ZNF596 in open-access papers:
ZNF596 is named in the same sentence as 10 diseases in open-access papers, as found by Europe PMC text mining. Sharing a sentence is not in itself a finding about the gene and the disease. The quoted sentences say what the papers report.
glioma (2 papers, 2021 to 2022). A benign or malignant brain and spinal cord tumor that arises from glial cells (astrocytes, oligodendrocytes, ependymal cells). "In glioma cells, lncRNA LINC00115 promotes the sphere formation of stem-like cancer cells in vitro and tumor growth in vivo via sponging miR-200s to reduce their binding on the 5′UTR of ZNF596, a downstream stemness regulator of glioma cells." (PMID 35736633, 2022).
multiple sclerosis (1 paper, 2023). A progressive autoimmune disorder affecting the central nervous system resulting in demyelination. "Characterized by lesions in the central nervous system disseminated in time and space, ZNF596 has been reported to be involved in the pathogenesis of multiple sclerosis." (PMID 36979105, 2023).
tumour (1 paper, 2023). "This attenuation of miR-200s by LINC00115 also promoted zinc finger protein 596 (ZNF596) transcription, thus activating ZNF596/EZH2/STAT3 signalling and increasing GSC self-renewal as well as tumour growth in vivo." (PMID 37239035, 2023).
ZNF596 also shares sentences with these, for which no sentence is quoted: autoimmune disease (1 paper); breast carcinoma (1); cancer (1); diabetes (1); diabetes retinopathy (1); gestational diabetes (1); nephrogenic diabetes insipidus (1).